AMACR (alpha-methylacyl-CoA racemase)
Diseases named in the same sentence as AMACR in open-access papers (continued):
Sharing a sentence is not in itself a finding about the gene and the disease.
infection (4 papers, 2018 to 2025). The state of being infected such as from the introduction of a foreign agent such as serum, vaccine, antigenic substance or organism. "The infection with Ad5/3+AMACR 565 bp+A.TSTA was shown to not be significant in MR42Ds due to high variability." (PMID 30613352, 2018).
gastrointestinal tumours (1 paper, 2013). "Until now only few studies focussed on AMACR expression in gastrointestinal tumours." (PMID 24152881, 2013).
neurological disorders (1 paper, 2020). "Therefore, the deficiency of AMACR or protein inactivation causes neurological disorders due to the accumulation of branched-chain fatty acids and is also associated with various peroxisome disorders." (PMID 32760737, 2020). "A decrease in AMACR activity leads to an increase in R-2 methyl fatty acids, which leads to human nervous system disorders." (PMID 32760737, 2020).
peripheral neuropathy (1 paper, 2013). A disorder affecting the peripheral nervous system. "Homozygous AMACR gene mutations are known to cause α-methylacyl-coA racemase deficiency, comprising peripheral neuropathy, seizures and relapsing encephalopathy with MRI findings resembling those found in our patients." (PMID 23286897, 2013).
AMACR also shares sentences with these, for which no sentence is quoted: prostate (5 papers); clear cell renal cell carcinoma (3); chromophobe carcinomas (2); colon adenoma (2); kidney cancer (2); lung carcinoma (2); Nephroblastoma (2); oculocutaneous albinism (2); papillary adenoma (2); squamous carcinoma (2); Adrenal insufficiency (1); alcohol abuse (1); AMACR deficiency (1); amyotrophic lateral sclerosis (1); Arthritis (1); arthropathy (1); Atrophy (1); bladder cancer (1); brain cancer (1); breast carcinoma (1); carcinoids (1); carcinoma in situ (1); cerebrotendinous xanthomatosis (1); cervical carcinoma (1); Cirrhosis (1); co-infection (1); colitis (1); colorectal adenocarcinoma (1); congenital malformations (1); cutaneous melanoma (1).
A further 34 diseases each share a sentence with AMACR in 1 paper.